IL20RB (interleukin 20 receptor subunit beta)
Diseases named in the same sentence as IL20RB in open-access papers (continued):
Sharing a sentence is not in itself a finding about the gene and the disease.
tumor (continued). "Indeed, calcipotriol treatment showed markedly reduced efficacy in controlling Il20rb–/– PyMt tumor growth compared with WT PyMt tumor." (PMID 39782693, 2025). "Importantly, IL20RB neutralization with antibodies reduced the metastatic potential of tumor cells in vivo; therefore this becomes a relevant strategy to be evaluated in clinical trials in order to manage bone metastases in advanced stages." (PMID 39737401, 2024). "Notably, IL20RB knockdown combined with gemcitabine treatment further reduced tumor volume and weight compared with IL20RB knockdown alone or gemcitabine treatment alone." (PMID 38098005, 2023). "Consequently, IL-19 promotes the activation of IL-20RB-expressing tumor cells, activating the JAK1/signal transducer and activating the transcription 3 (STAT3) signaling pathway." (PMID 38260135, 2023). "Moreover, the IL20RB knockdown group displayed significantly smaller tumor volumes and weights than the control group." (PMID 38098005, 2023). "Notably, IL20RB overexpression upregulated the mRNA levels of several tumor stemness markers, including NANOG, SOX2 and POU5F1, while IL20RB knockdown downregulated their mRNA levels." (PMID 38098005, 2023). "IL20RB expression was significantly higher in tumor tissues than in normal tissues." (PMID 35883015, 2022). "Results indicate that IL20RB is more likely to act as a cytokine receptor, and tumor samples with high IL20RB expression are more likely to enrich pathways related to immune response such as cytokine-cytokine receptor interaction and intestinal immune network for IgA production." (PMID 35299868, 2022). "Confirming this hypothesis, administration of an IL-19–neutralizing antibody in the osteoclastic CM blocked the effect of CM in promoting organoid formation of IL20RB-expressing tumor cells." (PMID 36006737, 2022). "Results support that the higher IL20RB expression is, the higher tumor grade will be." (PMID 35299868, 2022). "In addition, STAT3 inhibitors, including stattic and napabucasin, suppressed STAT3 phosphorylation and activation in IL20RB-expressing tumor cells after stimulation by osteoclastic CM or IL-19, leading to inhibition of organoid formation." (PMID 36006737, 2022). "IL20RB knockdown impaired the responsiveness of tumor cells to recombinant IL-19." (PMID 36006737, 2022). "By 5-ethynyl-2′-deoxyuridine (EdU) labeling 24 hours prior to bone harvest from the mice, it was found that higher percentages of IL20RB-overexpressing tumor cells were active in proliferation, while knockdown of IL20RB suppressed proliferation of tumor cells in bone." (PMID 36006737, 2022). "IL-20RB enhances proliferation of tumor cells in bone and promotes bone metastasis." (PMID 36006737, 2022). "A strong positive correlation was also observed between IL20RB expression and tumor grade." (PMID 35299868, 2022). "More importantly, intraperitoneal treatment of the mice with napabucasin after intracardiac inoculation of IL20RB-expressing A549 cells was able to suppress proliferation of tumor cells disseminated in the bone, with bone lysis and bone metastasis effectively prevented." (PMID 36006737, 2022). "IL20RB may play as a tumor driver gene in ccRCC by participating immune response; there seemingly exists crosstalk between IL20RB and neutrophils." (PMID 35299868, 2022). "Osteoclast-secreted IL-19 activates JAK1/STAT3 signaling in IL20RB-expressing tumor cells." (PMID 36006737, 2022). "The characteristic “inflammatory–stromal” tumor microenvironment observed in the high-ITH, high-risk subgroup, together with IL20RB-driven proliferative and invasive advantages at the clonal level, may jointly underlie the poor clinical outcomes in this population." (PMID 41562081, 2025).
tumor (continued). "However, when A549 cells were treated with conditioned medium (CM) of osteoclasts, the proliferation of IL20RB-overexpressing tumor cells, as measured by EdU labeling, was markedly stimulated by the CM, while the control A549 cells demonstrated no response from osteoclastic CM." (PMID 36006737, 2022). "Interestingly, tumor cells with strong or weak metastatic proclivities can all induce IL-19 secretion of osteoclasts, but their responsiveness toward osteoclasts is dependent on IL-20RB expression." (PMID 36006737, 2022). "Also, AGER and IL20RB have been reported as tumor promoters in ccRCC." (PMID 33681201, 2021). "Additional examination of the link between tumor-infiltrating immune cells (TIIC) and IL20RB was executed utilizing the Tumor Immune Estimation Resource (TIMER) and TISIDB databases." (PMID 41836171, 2026). "IHC of tumor tissue sections showed that the protein levels of NANOG and SOX2 in the IL20RB knockdown group was significantly lower than those in the control group." (PMID 38098005, 2023). "By examining their expression in Xenabrowser, we found that HMGA2 and IL20RB were positively correlated with GRIN2D expression and highly expressed in PDAC tumor tissues." (PMID 37553583, 2023). "Western blot analysis of tumor tissues validated that the protein expression of NANOG and SOX2 was significantly lower in the IL20RB knockdown group than in the control group." (PMID 38098005, 2023). "Mechanistically, tumor cells induced osteoclasts to secrete the IL-20RB ligand IL-19, and IL-19 stimulated IL-20RB–expressing tumor cells to activate downstream JAK1/STAT3 signaling, leading to enhanced proliferation of tumor cells in bone." (PMID 36006737, 2022). "Among them, TDGF1, and GRP were up-regulated in tumor samples, while NRG1, CRLF1, and IL20RB were down-regulated in tumor samples." (PMID 35748788, 2022). "Tumor cell proliferation in the bone was also reduced after STAT3 knockdown, abolishing the proproliferation effect of IL20RB." (PMID 36006737, 2022). "To have a perceptual panoramic view of IL20RB's role in cancers, we used the pan-cancer view function of UALCAN to visualize the expression profile of IL20RB in 24 tumor types." (PMID 35299868, 2022). "A total of 30 IL22RA1-correlated genes (e.g. IL17D, IL22RA2, IL20RB, IL10RA, IL10RB, TSLP and TYK2) are involved in the JAK/STAT pathway which promotes tumor progression." (PMID 35874683, 2022). "Tumor Immune Estimation Resource (TIMER) and Tumor and Immune System Interaction Database (TISIDB) were utilized to determine the correlation of IL20RB expression levels with tumor-infiltrating immune cells (TIICs)." (PMID 35883015, 2022). "As expected, the expression of IL20RB, MET, OASL, and PLAU in tumor tissues was significantly higher than that in normal tissues." (PMID 34335699, 2021). "Surprisingly, neither IL20RB knockdown nor overexpression in tumor cells obviously altered the abundance of TRAP+ osteoclasts along the tumor-bone interface." (PMID 36006737, 2022). "Although IL20RB increased the sphere formation ability at a relatively low cell density (103/well), it had no influence on tumor-initiation ability, as measured by ELDA in vivo." (PMID 33456560, 2021). "These pathways are more likely to function in normal renal cells which may indicate that tumor samples of the IL20RB low expression group are more like normal tissues and have a better histologic differentiation thereby a lower malignancy phenotype." (PMID 35299868, 2022). "Incubating tumor cells in osteoclastic CM led to a noticeable rise of JAK1 and STAT3 phosphorylation in IL20RB-overexpressing A549 cells, but not in control A549 cells." (PMID 36006737, 2022).
cancer (22 papers, 2015 to 2025). A tumor composed of atypical neoplastic, often pleomorphic cells that invade other tissues. "On the other hand, the association with BAP1 somatic cancer driver mutations (P = 0.019) and IL20RB expression (P = 0.223) appeared to be ccRCC specific (Dataset EV5)." (PMID 39592856, 2024). "IL20RB may function as an immune-associated therapeutic target for it determines cancer progression and regulates immune cell infiltration in ccRCC." (PMID 35883015, 2022). "In the present study, we found that the STAT3 signaling pathway played an important role in mediating the function of IL20RB in promoting cancer stemness and chemoresistance, and IL20RB-STAT3 signaling promoted the expression of NANOG, SOX2 and POU5F1." (PMID 38098005, 2023). "When these cancer cells were intracardiacally inoculated into immunodeficient nude mice, IL20RB overexpression significantly accelerated bone metastasis, resulting in exacerbated bone damage, but had no influence on the metastasis to other nonbone organs." (PMID 36006737, 2022). "The expression levels of IL20RB were significantly increased in multiple cancer types, including kidney renal clear cell carcinoma (KIRC) (p < 0.001)." (PMID 35883015, 2022). "STAT3 activation by osteoclastic CM in IL20RB-expressing cancer cells was also confirmed with a STAT3 luciferase reporter." (PMID 36006737, 2022). "Then, we used the ‘Gene DE module’ of the TIMER database to analyze the differential expression of IL20RB in pan-cancer." (PMID 35883015, 2022). "Indeed, this epigenetic effect was particularly pronounced for IL20RB and WT1 in the presence of BAP1 somatic cancer driver mutations (Fig. EV5)." (PMID 39592856, 2024). "Eventually, IL20RB overexpression has been correlated with a high rate of cell invasion and migration, a higher grade of cell proliferation, and a poor prognosis in different types of carcinoma, especially that of the kidney." (PMID 38732382, 2024). "IL20RB, interleukin 20 receptor subunit beta, is a cytokine receptor subunit coding gene and was initially found to play a vital role in human cancers, while its role in ccRCC still remains unclear." (PMID 35299868, 2022). "Aberrant expression of IL-20RB has also been reported in various cancer types." (PMID 36006737, 2022). "In this study, we are mainly focused on IL20RB, whose role in ccRCC is still unknown but has shown its potential as a novel biomarker in some human cancers." (PMID 35299868, 2022). "These indicate that IL20RB may mainly function as interleukin receptor and promote cancer development by the JAK-STAT pathway." (PMID 35299868, 2022). "Recently, increasing evidence supports IL20RB also plays a vital role in human cancers such as colorectal adenocarcinoma, breast cancer, and esophageal carcinoma, while its role in ccRCC still remains unclear." (PMID 35299868, 2022). "IL20RB expression levels have already been documented in several cancers." (PMID 36553569, 2022). "In addition, cancer cells incubated in the CM of control or IL20RB-overexpressing A549 cells demonstrated no proliferative difference, indicating that IL-20RB mediated the tumoral response to a paracrine factor." (PMID 36006737, 2022).
infection (4 papers, 2020 to 2024). The state of being infected such as from the introduction of a foreign agent such as serum, vaccine, antigenic substance or organism. "Despite having similar fungal burdens, the il20rb-/- mice exhibited less weight loss over the course of infection compared to the B6 mice." (PMID 36225230, 2022). "When challenged with OA1, which causes increased weight loss compared to the parental strain CAF2-1, the il20rb-/- group not only recovered its initial mean weight but showed weight gain on Day 4, indicative of recovery from infection." (PMID 36225230, 2022). "Despite comparable fungal burdens, the Il20rb-/- mice exhibited less weight loss over the course of their infection compared to the B6 mice, suggestive of reduced overall disease consequences in the mutant mice." (PMID 36225230, 2022). "Meanwhile, using qRT-PCR, we also detected the transcription of il20rb and one of its alpha chain il20ra1 in HaCaT cells after infection by RH-WT and RH-Δrop18 at 5, 10, 20, and 30 min post-infection." (PMID 32767999, 2020). "Using WB, the translation of il20rb in HaCaT cells after treatment with 400 ng of IL-20 and infection by RH-WT or RH-Δrop18 was detected at 30 min post-infection." (PMID 32767999, 2020). "Our results indicated that both the transcription and translation of IL20RB was not affected by TgROP18 until after 30 min post-infection." (PMID 32767999, 2020).
IL20RB also shares sentences with these, for which no sentence is quoted: asthma (3 papers); vitiligo (3); bladder cancer (2); gastric cancer (2); liver cancer (2); rheumatoid arthritis (2); anal carcinoma (1); and Central Nervous System cancer (1); Arthritis (1); blood cancers (1); carpal tunnel syndrome (1); cervical cancer (1); Chronic myeloid leukemia (1); chronic rhinosinusitis (1); colon cancer (1); colorectal adenocarcinoma (1); contact dermatitis (1); COVID-19 (1); endometriosis (1); esophageal cancer (1); fibrosarcoma (1); Glucose intolerance (1); Immunodeficiency (1); infectious disease (1); inflammation (1); intraductal cribriform breast adenocarcinoma (1); liver fibrosis (1); lupus nephritis (1); metabolic syndrome (1); neurologic diseases (1).
A further 10 diseases each share a sentence with IL20RB in 1 paper.